MIR185 (microRNA 185)
Synonyms: hsa-mir-185; MIRN185; miR-185
Gene: MicroRNA gene on chromosome 22 (20,033,139 to 20,033,220, forward strand). Ensembl gene ENSG00000208023.
Gene Ontology:
Biological process: miRNA-mediated post-transcriptional gene silencing
Cellular component: RISC complex
Homologues: Orthologues: chimpanzee ptr-mir-185 (100% identical), macaque mml-mir-185 (98% identical), rat Mir185 (95% identical), pig ssc-mir-185 (91% identical), mouse Mir185 (79% identical), guinea pig MIR185 (78% identical), rabbit MIR185 (67% identical).
Diseases named in the same sentence as MIR185 in open-access papers:
MIR185 is named in the same sentence as 2 diseases in open-access papers, as found by Europe PMC text mining. Sharing a sentence is not in itself a finding about the gene and the disease. The quoted sentences say what the papers report.
schizophrenia (2 papers, 2013 to 2018). A major psychotic disorder characterized by abnormalities in the perception or expression of reality. "Further schizophrenia-associated miRNA from the 22q11.2 region include MIR185, a miRNA that was first implicated in schizophrenia through mouse studies." (PMID 29657307, 2018). "However, despite a number of systematic investigations of genes in the 22q11.2DS region and the ever increasing number of GWAS data sets, no genetic study to date has identified common variation in DGCR8 or MIR185 as a risk factor for schizophrenia." (PMID 24367288, 2013).
kidney diseases (1 paper, 2024). "Previously, it was described that RHOA knockdown (the effect observed in HEK MIR185 KOhom cell line) in podocytes led to increased apoptosis, a process commonly associated with the development of kidney diseases." (PMID 38413914, 2024).